CACNB1 (calcium voltage-gated channel auxiliary subunit beta 1)
Description:
Regulatory subunit of L-type calcium channels. Regulates the activity of L-type calcium channels that contain CACNA1A as pore-forming subunit (By similarity). Regulates the activity of L-type calcium channels that contain CACNA1C as pore-forming subunit and increases the presence of the channel complex at the cell membrane. Required for functional expression L-type calcium channels that contain CACNA1D as pore-forming subunit. Regulates the activity of L-type calcium channels that contain CACNA1B as pore-forming subunit.
Synonyms: CAB1; CACNLB1; CCHLB1
Tractability: Small molecule: an approved drug acts on it; a structure with a bound ligand is known; a high-quality ligand is known; it belongs to a druggable protein family. Antibody: UniProt places it where antibodies can reach, with high confidence; its Gene Ontology location is reachable by antibodies, with high confidence. PROTAC: ubiquitination databases record sites on it; its protein half-life has been measured; a small molecule that binds it is known.
Gene: Protein-coding gene on chromosome 17 (39,173,453 to 39,197,723, reverse strand). Ensembl gene ENSG00000067191.
Subcellular location: Cell membrane, sarcolemma; Cell membrane
Pathways (Reactome):
Muscle contraction: Phase 0 - rapid depolarisation; Phase 2 - plateau phase
Cellular responses to stimuli: Mechanical load activates signaling by PIEZO1 and integrins in osteocytes
Developmental Biology: NCAM1 interactions
Neuronal System: Presynaptic depolarization and calcium channel opening
Gene Ontology:
Molecular function: calcium channel regulator activity; protein binding; high voltage-gated calcium channel activity; voltage-gated calcium channel activity
Biological process: cellular response to amyloid-beta; regulation of calcium ion transmembrane transport via high voltage-gated calcium channel; calcium ion transmembrane transport; calcium ion transport; chemical synaptic transmission; positive regulation of muscle contraction
Cellular component: voltage-gated calcium channel complex; L-type voltage-gated calcium channel complex; plasma membrane; T-tubule; sarcolemma; synapse
Genetic constraint (gnomAD): Loss-of-function variants: 23 observed, 58.6 expected, observed/expected ratio (o/e) 0.39, 90% interval 0.28 to 0.56. The upper end of that interval is the gene's LOEUF score, 0.56, which puts it in group 2 of 6, group 1 being the genes least tolerant of losing a copy. Missense variants: 572 observed, 741.72 expected, observed/expected ratio (o/e) 0.77, 90% interval 0.72 to 0.83. Synonymous variants: 278 observed, 301.63 expected, observed/expected ratio (o/e) 0.92, 90% interval 0.83 to 1.02.
Homologues: Orthologues: macaque CACNB1 (99% identical), dog CACNB1 (98% identical), pig CACNB1 (98% identical), mouse Cacnb1 (97% identical), rat Cacnb1 (97% identical), guinea pig CACNB1 (94% identical), rabbit CACNB1 (94% identical), chimpanzee CACNB1 (93% identical), tropical clawed frog cacnb1 (75% identical), zebrafish cacnb1 (75% identical), Drosophila melanogaster Ca-beta (50% identical), Caenorhabditis elegans ccb-1 (45% identical), and 1 more. Paralogues in human: CACNB2 (67% identical), CACNB4 (55% identical), CACNB3 (48% identical).
Diseases named in the same sentence as CACNB1 in open-access papers:
CACNB1 is named in the same sentence as 18 diseases in open-access papers, as found by Europe PMC text mining. Sharing a sentence is not in itself a finding about the gene and the disease. The quoted sentences say what the papers report.
cardiac hypertrophy (2 papers, 2016 to 2020). "The genes in this category are linked to a variety of cardiac abnormalities ranging from cardiac signaling pathway, calcium muscle contraction (Cacnb1), cardiac hypertrophy and fibrosis and stress response." (PMID 27548259, 2016). "Previous studies have confirmed that miR‐195 expression is increased in cardiac hypertrophy, and the bioinformatics website predicted by Targetscan software shows that miR‐195 can directly target CACNB1, KCNJ2 and KCND3 to regulate Cavβ1, Kir2.1 and Kv4.3 proteins expression." (PMID 32468736, 2020).
Malignant hyperthermia (2 papers, 2014 to 2023). Malignant hyperthermia is characterized by a rapid increase in temperature to 39-42 degrees C. Malignant hyperthermia may occur in response to either inhalational anesthetics such as halothane, to muscle relaxants such as succinylcholine, or to exercise. "CACNB1 codes for the beta subunit of a voltage-dependent calcium channel and its dysregulation has been linked to pathological conditions, including malignant hyperthermia and headache." (PMID 37026480, 2023). "However, CACNG1, CACNB1 and CACNA2D1 encode for subunits of the DHPR calcium channel, which is in direct contact and regulating RYR1 in skeletal muscle, and one mutation in the channel subunit CACNA1S of DHPR was linked to malignant hyperthermia." (PMID 25353622, 2014).
esophageal cancer (1 paper, 2021). A primary or metastatic malignant neoplasm involving the esophagus. "It has been pointed out that CACNB1 (also known as CAB1) was overexpressed in gastric and esophageal cancer cells." (PMID 34881275, 2021).
high blood pressure (1 paper, 2018). "For instance, CACNB1 is a calcium channel protein and the inhibitor amlodipine is one of the most popular medications for treatment of high blood pressure." (PMID 30123134, 2018).
hypertrophic cardiomyopathy (1 paper, 2017). A condition in which the myocardium is hypertrophied without an obvious cause. "Due to the relatively low number of detected down-regulated genes, only one pathway was found to be significant, and it contained genes overexpressed at the start of the training schedule (T1): hypertrophic cardiomyopathy (HCM) pathway (CACNB1, TPM1, TPM2, TTN)." (PMID 28381206, 2017).
kidney cancer (1 paper, 2021). Primary or metastatic malignant neoplasm involving the kidney. "While only weak correlation was uncovered between BCL2L13 and the known kidney cancer related genes, we found that voltage-dependent L-type calcium channel subunit beta-1 (CACNB1) and numb-like protein (NUMBL) are the two BCL2L13 negatively correlated genes." (PMID 34193180, 2021).
Sepsis (1 paper, 2019). Sepsis is defined as life-threatening organ dysfunction caused by a dysregulated host response to infection. "Previous research has described an increased expression of synaptic genes during the progression from normal aging to neurodegenerative disease, including genes we observed to increase in older males on day 4 of sepsis (Cacnb1, Cacna1a, Ephb4, Glul, Jph3, Mink1, Nrxn2, Grasp)." (PMID 31278440, 2019).
viral infection (1 paper, 2022). "Using a pooled shRNA screen to identify ion channels that regulate T cell responses to viral infection in vivo, we find that deletion of Cacnb1 impairs the clonal expansion of antigen specific T cells after viral infection in vivo by enhancing T cell apoptosis." (PMID 35440113, 2022).
infection (1 paper, 2022). The state of being infected such as from the introduction of a foreign agent such as serum, vaccine, antigenic substance or organism. "We next investigated the ability of Cacnb1-deficient T cells to expand after infection of mice with LCMVARM." (PMID 35440113, 2022).
CACNB1 also shares sentences with these, for which no sentence is quoted: autism (1 paper); autism spectrum disorder (1); ciliopathies (1); epilepsy (1); fragile X syndrome (1); Intellectual disability (1); neurodegenerative disease (1); tumor (1); Ventricular arrhythmia (1).